ACOT4 (acyl-CoA thioesterase 4)
Description:
Catalyzes the hydrolysis of acyl-CoAs into free fatty acids and coenzyme A (CoASH), regulating their respective intracellular levels. Functions as a peroxisomal succinyl-coenzyme A thioesterase that can also hydrolyze glutaryl-CoA and long chain saturated acyl-CoAs.
Synonyms: PTE-Ib; PTE2B; FLJ31235; PTE1B
Tractability: Small molecule: it has a high-quality binding pocket. PROTAC: ubiquitination databases record sites on it; its protein half-life has been measured.
Gene: Protein-coding gene on chromosome 14 (73,591,873 to 73,595,766, forward strand). Ensembl gene ENSG00000177465.
Subcellular location: Peroxisome
Pathways (Reactome):
Metabolism: Beta-oxidation of very long chain fatty acids
Protein localization: Peroxisomal protein import
Gene Ontology:
Molecular function: fatty acyl-CoA hydrolase activity; succinyl-CoA hydrolase activity; acyl-CoA hydrolase activity; long-chain fatty acyl-CoA hydrolase activity; medium-chain fatty acyl-CoA hydrolase activity; thiolester hydrolase activity
Biological process: acyl-CoA metabolic process; butyrate metabolic process; dicarboxylic acid catabolic process; dicarboxylic acid metabolic process; long-chain fatty acid metabolic process; saturated monocarboxylic acid metabolic process; short-chain fatty acid metabolic process; succinyl-CoA metabolic process; unsaturated monocarboxylic acid metabolic process; very long-chain fatty acid metabolic process; fatty acid biosynthetic process; lipid metabolic process; monocarboxylic acid metabolic process
Cellular component: peroxisome; cytosol; peroxisomal matrix
Genetic constraint (gnomAD): Loss-of-function variants: 14 observed, 13.69 expected, observed/expected ratio (o/e) 1.02, 90% interval 0.67 to 1.59. The upper end of that interval is the gene's LOEUF score, 1.59, which puts it in group 6 of 6, group 1 being the genes least tolerant of losing a copy. Missense variants: 467 observed, 470.5 expected, observed/expected ratio (o/e) 0.99, 90% interval 0.92 to 1.07. Synonymous variants: 190 observed, 189.7 expected, observed/expected ratio (o/e) 1, 90% interval 0.89 to 1.13.
Homologues: Orthologues: chimpanzee ACOT4 (99% identical), guinea pig ACOT4 (78% identical), rat Acot4 (77% identical), mouse Acot4 (74% identical), tropical clawed frog acot2 (52% identical), tropical clawed frog jmjd7 (46% identical), zebrafish acot21 (45% identical), zebrafish acot20 (44% identical), zebrafish acot22 (43% identical), Caenorhabditis elegans W03D8.8 (30% identical), Caenorhabditis elegans K05B2.4 (28% identical), Caenorhabditis elegans T05E7.1 (26% identical), and 1 more. Paralogues in human: ACOT1 (70% identical), ACOT2 (70% identical), ACOT6 (66% identical), BAAT (45% identical).
Diseases named in the same sentence as ACOT4 in open-access papers:
ACOT4 is named in the same sentence as 13 diseases in open-access papers, as found by Europe PMC text mining. Sharing a sentence is not in itself a finding about the gene and the disease. The quoted sentences say what the papers report.
liver steatosis (3 papers, 2015 to 2024). "Following Acot4 overexpression, there was a significant upregulation of free fatty acid levels in the plasma and liver of mice, leading to increased lipid accumulation in the liver and subsequent hepatic steatosis." (PMID 39329770, 2024). "Among the highest up-regulated protein coding genes in obese males were Acot4 (1.82 fold, p = 0.022), Cyp4a10 (1.35 fold, p = 0.026) and Cyp4a14 (1.32 fold, p = 0.012), which hydroxylize fatty acids and which are known to be increased in liver steatosis." (PMID 26546267, 2015).
atherosclerosis (2 papers, 2024). A disease characterized by the build-up of fatty material and calcium deposition in the arterial wall resulting in partial or complete occlusion of the arterial lumen. "On the other hand, our study shows that the Pep_A6 vaccine can regulate the expression of liver genes such as Fitm2, Gk, Plin2, Acsl1, Fatp1, and Acot4, thereby lowering serum LDL-C levels and hepatic lipid accumulation while improving atherosclerosis." (PMID 39329770, 2024).
Obesity (2 papers, 2020 to 2025). Accumulation of substantial excess body fat. "Novel high impact variants resulting in premature stop codons were identified in the following genes associated with enriched obesity pathways in Meishan pigs: PLIN1 (adipogenesis, white adipose tissue browning), GRB10 (insulin receptor signaling), and ACOT4 (stearate biosynthesis I)." (PMID 40340757, 2025). "Several obesity- and lipid-metabolism-related genes were differentially expressed in the testis of obese rats, including fatty acid synthesis, such as acyl-CoA thioesterase 4 (O/C −10.75) or fatty acid elongation, including 3-hydroxyacyl-CoA dehydratase 4 (O/C 4.81)." (PMID 32899471, 2020).
gastric cancer (1 paper, 2022). A primary or metastatic malignant neoplasm involving the stomach. "Individualized therapy targeting ACOT4 might also be a promising modality for the treatment of gastric cancer patients." (PMID 35785165, 2022).
Insulin resistance (1 paper, 2025). Increased resistance towards insulin, that is, diminished effectiveness of insulin in reducing blood glucose levels. "Loss of ACOT4 in mice can disrupt insulin signaling and exacerbate insulin resistance induced by a high-fat diet." (PMID 40941321, 2025).
lipid metabolic disorders (1 paper, 2025). "ACOT1, ACOT4, and ACOT6 are acyl-CoA thioesterases that catalyze the hydrolysis of acyl-CoA into FFAs and CoASH, playing key roles in fatty acid metabolism, and their regulation may help alleviate lipid metabolic disorders." (PMID 41194880, 2025).
mastitis (1 paper, 2024). Inflammation of breast tissue during lactation or postpartum due to an obstructed duct or infection. "Among them, three (ACOT4, PDLIM5, and RAB11FIP5) were also selected as discriminant genes driving the major changes in gene expression profiles of key gene modules related to S. aureus subclinical mastitis in our previous transcriptome analysis." (PMID 38486242, 2024).
pancreatic ductal carcinoma (1 paper, 2023). "For example, ACOT4 expression is potentiated in pancreatic ductal carcinoma (PDAC)." (PMID 37003979, 2023).
psoriasis (1 paper, 2024). An autoimmune condition characterized by red, well-delineated plaques with silvery scales that are usually on the extensor surfaces and scalp. "Other psoriasis-specific enriched pathways included lipid metabolism (e.g. ACOT4, S1PR3), keratinization (e.g. LCE5A, KRT5/7/16), neutrophil degranulation, and antimicrobial peptides (e.g. LTF, DEFB4A, S100A7-9)." (PMID 38433843, 2024).
ACOT4 also shares sentences with these, for which no sentence is quoted: invasive carcinoma (1 paper); iron deficiency (1); metabolic syndrome (1); vitiligo (1).